PODXL (podocalyxin like)
Description:
Involved in the regulation of both adhesion and cell morphology and cancer progression. Functions as an anti-adhesive molecule that maintains an open filtration pathway between neighboring foot processes in the podocyte by charge repulsion. Acts as a pro-adhesive molecule, enhancing the adherence of cells to immobilized ligands, increasing the rate of migration and cell-cell contacts in an integrin-dependent manner. Induces the formation of apical actin-dependent microvilli. Involved in the formation of a preapical plasma membrane subdomain to set up initial epithelial polarization and the apical lumen formation during renal tubulogenesis. Plays a role in cancer development and aggressiveness by inducing cell migration and invasion through its interaction with the actin-binding protein EZR. Affects EZR-dependent signaling events, leading to increased activities of the MAPK and PI3K pathways in cancer cells.
Synonyms: PC; PCLP-1; PCLP; Gp200; PODXL1; PDX; gp135
Tractability: Antibody: its Gene Ontology location is reachable by antibodies, with high confidence; UniProt places it where antibodies can reach, with medium confidence; UniProt predicts a signal peptide or a membrane-spanning region. PROTAC: ubiquitination databases record sites on it.
Gene: Protein-coding gene on chromosome 7 (131,500,254 to 131,558,217, reverse strand). Ensembl gene ENSG00000128567.
Subcellular location: Apical cell membrane; Cell projection, lamellipodium; Cell projection, filopodium; Cell projection, ruffle; Cell projection, microvillus; Membrane raft; Membrane
Subcellular location (Human Protein Atlas): Endoplasmic reticulum; Plasma membrane; Centriolar satellite; Nucleoli; Vesicles
Gene Ontology:
Molecular function: protein binding
Biological process: positive regulation of cell migration; positive regulation of cell-cell adhesion mediated by integrin; cell migration; epithelial tube formation; negative regulation of cell adhesion; negative regulation of cell-cell adhesion; podocyte development; regulation of microvillus assembly; regulation of cell-cell adhesion
Cellular component: cytoplasm; extracellular exosome; extracellular region; filopodium; lamellipodium; plasma membrane; ruffle; apical plasma membrane; microvillus membrane; slit diaphragm; membrane; membrane raft; microvillus
Genetic constraint (gnomAD): Loss-of-function variants: 19 observed, 46.06 expected, observed/expected ratio (o/e) 0.41, 90% interval 0.29 to 0.61. The upper end of that interval is the gene's LOEUF score, 0.61, which puts it in group 2 of 6, group 1 being the genes least tolerant of losing a copy. Missense variants: 601 observed, 671.75 expected, observed/expected ratio (o/e) 0.89, 90% interval 0.84 to 0.96. Synonymous variants: 293 observed, 279.21 expected, observed/expected ratio (o/e) 1.05, 90% interval 0.95 to 1.16.
Homologues: Orthologues: chimpanzee PODXL (90% identical), macaque PODXL (67% identical), dog PODXL (41% identical), mouse Podxl (39% identical), rat Podxl (37% identical), tropical clawed frog podxl (26% identical), zebrafish podxl (18% identical).
Diseases named in the same sentence as PODXL in open-access papers:
PODXL is named in the same sentence as 134 diseases in open-access papers, as found by Europe PMC text mining. Sharing a sentence is not in itself a finding about the gene and the disease. The quoted sentences say what the papers report.
breast cancer (25 papers, 2013 to 2025). A primary or metastatic malignant neoplasm involving the breast. "PODXL expression is of particular interest since others have reported that high PODXL expression is associated with higher risk categories, and that breast carcinomas with high PODXL expression are more likely to exhibit characteristics of basal-like cancers." (PMID 35821504, 2022). "As an important regulator of metastasis, ezrin and its association with PODXL has recently been explored in breast cancer extravasation." (PMID 34201212, 2021). "Previous studies have shown that PODX overexpression is a predictor of breast cancer progression and that PODXL gene variants are associated with tumor aggressiveness." (PMID 24179530, 2013). "In particular, high PODXL expression has been associated with high-grade tumours, aggressive tumour phenotypes, and poor prognosis in breast cancer, colorectal cancer, gastric cancer, hepatocellular carcinoma, lung cancer including small cell lung carcinoma, and lung adenocarcinoma." (PMID 34201212, 2021). "PODXL is a negatively charged sialic acid glycoprotein, belonging to the type I transmembrane glycoprotein, which has been reported to be associated with poor prognosis in oral squamous cell carcinoma, colon cancer, glioblastoma, and breast cancer and has an impact on cell adhesion and migration." (PMID 36133435, 2022). "PODXL expression was found to be elevated in CTC clusters compared to single CTCs isolated from blood samples of breast cancer patients." (PMID 40843679, 2025). "A clone PODO83/PODOC, core protein-binding anti-PODXL mAb, suppressed breast cancer MDA-MB-231 xenograft growth and blocked lung metastasis." (PMID 40843679, 2025). "The activated transcription factor CREB accelerates breast cancer metastasis by upregulating metastasis-related gene expressions, such as PODXL, MMP3, and MMP9." (PMID 36923530, 2023). "This Ezrin dependence was further corroborated in breast cancer cells when studying the role of PODXL in tumor cell extravasation, which curiously reported the PODXL extracellular domain as dispensable for extravasation." (PMID 36735782, 2023). "Key work from the Roskelley and McNagny laboratories indicated that in breast cancer cells, PODXL drives an Ezrin-dependent collective migration and tumor-budding phenotype." (PMID 36735782, 2023). "We previously reported that PODXL overexpressed in MCF-7 breast cancer cell line accumulates at the interface formed with NK cells." (PMID 35711462, 2022). "Recently, we demonstrated that PODXL expressed in MCF-7 breast cancer cells localizes to the immune synapse formed upon contact with NK cells and acts as an immunomodulatory molecule." (PMID 35711462, 2022). "Subsequent studies with MCF-7 breast cancer cells show that overexpression of PODXL promotes the budding of cohesive nodules from the primary tumour in mice." (PMID 34201212, 2021). "PODXL overexpression in MCF-7 breast cancer cells, PC3 prostate cancer cells, as well as SGC-7901 gastric cancer cells, consistently enhances the mitogen-activated protein kinase (MAPK) and phosphatidylinositol 3-kinase (PI3K) signalling." (PMID 34201212, 2021). "In the highly metastatic breast cancer cell lines MDA-MB-231 and MDAMB-231, loss of PODXL reduces their ability to extravasate from in vitro endothelium, which is reversed by overexpression of PODXL." (PMID 34201212, 2021). "In MCF7 breast cancer cells, PODXL overexpression significantly inhibits T cell (CD4+ and CD8+) proliferation, supporting a previous study postulating an immunoregulatory role for PODXL in reducing T-lymphocyte proliferation in cardiac progenitor cells." (PMID 34201212, 2021). "In breast carcinoma models, tumour growth is significantly attenuated in mice injected with PODXL-knockdown cells, compared to controls which show significant cell proliferation." (PMID 34201212, 2021).
breast cancer (continued). "In NAMEC8R, MDA-MB-231, and MDA-MB-231 clone 4175 breast cancer cells, knockdown of PODXL significantly inhibited tumor dissemination to distant organs in murine xenograft models, an effect rescued by re-expressing wild type PODXL." (PMID 32046309, 2020). "In the highly aggressive MDA-MB-231 breast cancer cell line, suppression of PODXL decreased invadopodia formation and activation." (PMID 32046309, 2020). "On the other hand, PODXL overexpression in MCF-7 breast cancer cell line stimulated invadopodia formation and activation, through the induction of Rac1/Cdc42/cortactin signaling." (PMID 32046309, 2020). "Specifically, PODXL overexpression in MCF-7 breast cancer cells resulted in cell delamination from monolayers by perturbing cell junctions." (PMID 31083655, 2019). "A newly generated monoclonal antibody directed against an extracellular epitope of PODXL was used in immumohistochemistry to specifically detect PODXL expressing normal renal cells, as well as colorectal, and breast cancer cells." (PMID 31083655, 2019). "PODXL is expressed in many types of tumors including colorectal cancers, breast cancers, and brain tumors." (PMID 28384052, 2017). "Mounting evidence had demonstrated that PODXL, overexpressed in pancreatic cancer, hepatocellular, breast cancer, esophageal cancer, colorectal cancer and so forth, was considered as a tumor promoter." (PMID 28432273, 2017). "Overexpression of PODXL has been reported to correlate with a more aggressive phenotype of breast cancer, prostate cancer, and renal cell carcinoma." (PMID 24146797, 2013). "PODXL is hypothesised to mediate tumour budding because its overexpression positively correlates with the lymphovascular invasion of breast cancer cells." (PMID 34201212, 2021). "Therefore, extravasation in breast cancer cells appears to rely on PODXL-ezrin interactions, which likely enable cells to polarise and rearrange their cytoskeleton for transendothelial migration." (PMID 34201212, 2021). "Furthermore, in MCF-7 breast cancer and P3C prostate cancer cell lines, PODXL enhanced cell migration and invasion, matrix metalloproteinase 1 and 9 expression, and activation of MAPK and PI3K activity through its interaction with ezrin in in vitro assays." (PMID 32046309, 2020). "In MCF-7 breast cancer cells, forced expression of PODXL perturbed cell–cell junctions, a process which could facilitate breast carcinoma invasion." (PMID 32046309, 2020). "Additionally, recent study also revealed that the deletion of PODXL in breast cancer cells led to inhibition of primary tumor growth and metastasis in vivo." (PMID 29748877, 2019). "Furthermore, high PODXL expression was identified to be an independent factor for unfavorable prognosis in breast cancer patients." (PMID 31083655, 2019). "In agreement with this hypothesis, a previous work of our group demonstrated that PODXL expressed on MCF-7 breast cancer cell line accumulates at the immune synapse formed with NK cells and inhibits NK cell activity as well as agonist-induced CD4+ T and CD8+ T cell proliferation." (PMID 35711462, 2022). "High expression of PODXL, in particular in the membrane of tumour cells, has previously been demonstrated to correlate to an impaired prognosis in many major cancer forms like breast cancer, colorectal cancer, ovarian cancer, glioblastoma and urothelial bladder cancer." (PMID 28293425, 2017). "Furthermore, PcMab-47 stained PODXL-expressing cancer cells of colon or breast cancers." (PMID 28384052, 2017). "Emerging evidence showed that PODXL, normally expressed on vascular endothelial cells, hemangioblasts, podocytes and so on, had been found to be overexpressed in several cancers, such as pancreatic cancer, hepatocellular, breast cancer, esophageal cancer and gastric cancer and behaved as a oncogene." (PMID 28432273, 2017).
breast cancer (continued). "The upregulation of PODXL, MMP3 and MMP9 are believed to promote cell migration 48-50, suggesting CREB activation is critical for GPT2/GABA-induced breast cancer migration." (PMID 36923530, 2023). "PODXL knockdown in breast cancer cell line MDA-MB231 markedly impairs invadopodia formation by suppressing the Rac1/Cdc42/cortactin signalling network, whereas overexpression of PODXL enhances invadopodia development and consequent metastasis." (PMID 34201212, 2021). "Of note, a monoclonal antibody that preferentially bound to PODXL expressed on human tumor cells delayed tumor growth and metastasis to the lung in a mouse model using MDA-MB-231 breast cancer cells." (PMID 32046309, 2020). "To further confirm that podocalyxin has a causal role in promoting tumorsphere formation in vitro, we overexpressed PODXL in MCF7 cells (MCF7Podxl), a luminal-like human breast cancer cell line that expresses very low levels of endogenous podocalyxin." (PMID 25887862, 2015). "In breast cancer cells, the co-expression and interaction of EZR and PODXL increases the metastatic potential of the cells." (PMID 26135398, 2015). "PODXL has been shown to increase the invasive and migratory potential of MCF7 breast cancer and PC3 prostate cancer cells in vitro and leads to an increase in mitogen-activated protein kinase and phosphatidylinositol 3-kinase activity." (PMID 24146797, 2013). "On the contrary, we previously reported a lack of effect of PODXL expressed in MCF-7 breast cancer cells on the formation of MCF-7-NK cells conjugates." (PMID 35711462, 2022). "Forced expression of PODXL in HMLER, a breast cancer cell line with no detectable PODXL, also markedly increases cell ability to extravasate, further confirming the importance of PODXL in extravasation." (PMID 34201212, 2021). "We hypothesized that PODXL2 plays a similar role as PODXL in breast cancer, and increased PODXL2 expression in breast cancer promotes tumor progression." (PMID 32669966, 2020). "Besides, silencing of PODXL in both NAMEC8R and the highly metastatic MDA-MB-231 4175 breast cancer cells decreased extravasation in vitro, an effect which was totally reversed by overexpressing wild type PODXL." (PMID 32046309, 2020). "For example, breast cancer cell lines reportedly lack PSGL-1, but express CD44, CEA, and PODXL, much like LS174T cells, which may imply that their rolling adhesion behavior exhibits similar trends on P-, E- and L-selectin." (PMID 29137366, 2017). "Notably, aberrant overexpression of PODXL has been documented across a wide spectrum of human malignancies, including pancreatic ductal adenocarcinoma (PDAC), renal cell carcinoma, colorectal cancer, breast cancer, and oral squamous cell carcinoma." (PMID 40843679, 2025). "Recently, several studies indicated that PODXL might be a predictor of prognosis in various cancers, such as colorectal cancer (CRC), pancreatic cancer (PC), glioma, esophageal and gastric adenocarcinoma (EGAC), urothelial bladder cancer (UBC), breast cancer (BC) and so on." (PMID 28881743, 2017).
colorectal cancer (24 papers, 2012 to 2026). A primary or metastatic malignant neoplasm that affects the colon or rectum. "PODXL has been a candidate of therapeutic target and a diagnostic biomarker in PDAC and colorectal cancers since the high PODXL expression is a potential indicator of poor prognosis." (PMID 40843679, 2025). "High expression of PODXL has been linked to poor prognosis in a wide range of malignancies including gastrointestinal adenocarcinomas such as colorectal cancer, pancreatic and periampullary cancer and gastric cancer." (PMID 30355278, 2018). "The different expression patterns of the two antibodies suggests that they either recognise different variants of PODXL in colorectal cancer cells or that the antibodies catch PODXL at different stage on its way from cytoplasm to cellular membrane." (PMID 25004935, 2014). "Previous studies have shown that membranous expression of podocalyxin-like protein (PODXL) is associated with poor prognosis in colorectal cancer (CRC)." (PMID 23819542, 2013). "However, subgroup analysis showed a significant association between high expressed PODXL and poor OS in the colorectal cancer, pancreatic cancer, urothelial bladder cancer, renal cell carcinoma and glioblastoma multiforme." (PMID 32615943, 2020). "Radiation-induced PODXL promoted lamellipodia formation, migration, and invasiveness of colorectal cancer cells." (PMID 40843679, 2025). "Elevated expression of PODXL is significantly correlated with poor disease-free survival, cancer-specific survival, and overall survival in colorectal cancer, PDAC, renal cell carcinoma, urothelial bladder cancer, and glioblastoma multiforme." (PMID 40843679, 2025). "PODXL was identified as a target gene of β-catenin, which is frequently activated in colorectal cancer." (PMID 40843679, 2025). "The adverse prognostic role of PODXL expression in colorectal cancer (CRC) was first described only recently, and has since then been validated in several independent studies." (PMID 27160084, 2016). "Podocalyxin-like 1 (PODXL) is an anti-adhesive transmembrane protein that has been demonstrated to be an independent factor of poor prognosis in colorectal cancer (CRC)." (PMID 27160084, 2016). "In colorectal cancer about 94% of the cases were positive for PODXL with these two antibodies, whereas in gastric cancer positivity appeared in 76% cases with the monoclonal antibody and in 58% with the polyclonal antibody." (PMID 26674770, 2015). "In renal cell carcinoma, breast, and colorectal cancers, PODXL overexpression is an independent factor for poor outcome." (PMID 26053486, 2015). "For colorectal cancer patients with membranous PODXL expression by polyclonal antibody disease-specific survival (DSS) was significantly poorer (p = 0.001)." (PMID 25004935, 2014). "Kaplan-Meier analysis showed a significantly poorer disease-specific survival (DSS) for colorectal cancer patients with high PODXL expression (p = 0.011)." (PMID 25004863, 2014). "We recently demonstrated that overexpression of PODXL is an independent factor of poor prognosis in colorectal cancer (CRC)." (PMID 22769594, 2012). "Furthermore, PODXL was upregulated by radiotherapy in both colorectal cancer tissues and cultured cells." (PMID 40843679, 2025). "Previous studies in colorectal cancer also found distinct membranous staining of PODXL predominantly in a subset of infiltrating cells at the tumour front, which led to the suggestion that overexpression of PODXL is associated with invasive and metastatic properties." (PMID 38553472, 2024). "In 1983–2001, 840 consecutive colorectal cancer patients were treated at Helsinki University Central Hospital, of whom 767 were successfully scored for PODXL immunohistochemical expression from tumour tissue microarrays by use of a novel monoclonal in-house antibody." (PMID 25004863, 2014). "PODXL is an independent marker of poor prognosis in colorectal cancer." (PMID 25004935, 2014).
colorectal cancer (continued). "PODXL is upregulated in several types of cancer, and strong expression, in particular in the cell membrane, has been demonstrated to signify more aggressive tumours and poor prognosis in e.g. breast cancer, colorectal cancer ovarian cancer, urinary bladder cancer, and glioblastoma." (PMID 26028992, 2015). "A correlation and adverse prognostic synergy between PODXL and the epidermal growth factor receptor (EGFR) has been observed in colorectal cancer." (PMID 32587323, 2020). "Knockdown of PODXL in HCT116 and LOVO colorectal cancer cell lines suppressed cell proliferation and clonogenic potential, promoted apoptosis, and increased protein levels of caspase-3 and caspase-9, pointing to a role for PODXL in cell survival." (PMID 32046309, 2020). "Previous work has shown that high expression of PODXL and EGFR impair survival in colorectal cancer in a synergistic way25." (PMID 32587323, 2020). "In primary I-type carcinomas, membranous PODXL expression was denoted in 17.5 %, which is well in line with previous TMA-based studies on colorectal cancer wherein membranous expression was found in 13.4 % and 9.6 % respectively." (PMID 26028992, 2015). "Membranous expression of PODXL has been suggested to be an independent marker of poor prognosis in colorectal cancer (CRC), and previously by an in-house monoclonal antibody, we showed that also cytoplasmic overexpression of PODXL predicts poor prognosis." (PMID 25004935, 2014). "Patients with radiotherapy-resistant colorectal cancer may benefit from treatment interventions targeting TGF inhibition and PODXL activation." (PMID 37168510, 2023). "We also show that immunostaining of PODXL by our new in-house mAb gives prognostic results similar to those achieved by the commercial polyclonal antibody (HPA 2110, Atlas Antibodies, Stockholm, Sweden) in colorectal cancer." (PMID 26053486, 2015).